GAPDH (glyceraldehyde-3-phosphate dehydrogenase)
Diseases named in the same sentence as GAPDH in open-access papers (continued):
Sharing a sentence is not in itself a finding about the gene and the disease.
tumor (continued). "We analyzed the expression of BECN1 in relation to GAPDH in both tumor tissues and their corresponding adjacent normal tissues." (PMID 38787424, 2024). "GAPDH is a classical glycolytic enzyme that also acts as a moonlighting protein and is involved in tumor progression, invasiveness, and metastases." (PMID 38811918, 2024). "According to the results of PCR amplification and qPCR of human GAPDH gDNA, disseminated tumor cells were detected in the lungs of four out of six mice injected with PBS but not in the lungs of mice injected with IAA." (PMID 38649663, 2024). "The inhibition of glycolysis enables GAPDH to associate with the IFN-γ mRNA, preventing effective protein synthesis, thus reducing CTL cytokine secretion, and impairing their tumor-killing function." (PMID 39766353, 2024). "Regarding LUAD, the Wilcoxon rank sum test showed that GAPDH expression was considerably higher in tumor samples than it was in normal samples, and the pairing analysis between the normal and tumor tissues from the same patient produced similar results." (PMID 36837761, 2023). "Studies have demonstrated an increase in GAPDH expression levels in various tumor tissues and cells." (PMID 37671155, 2023). "In conclusion, a novel ferroptosis-related prognostic gene, GAPDH, was discovered, whose expression was connected to the tumor immune microenvironment." (PMID 36837761, 2023). "Differential analysis of the tumor microenvironment showed that the high GAPDH expression group had lower levels of immune cells and stromal cells." (PMID 36837761, 2023). "The CT values of GAPDH were measured to be 17.078–19.851 in NT tissues and 17.02–19.673 in tumor tissues, respectively." (PMID 37895312, 2023). "While cisplatin treatment prolonged the survival of all tumour-bearing animals, it synergized with GAPDH oxidation insensitivity, as the survival benefit was more pronounced in animals with mutant tumours." (PMID 37024754, 2023). "Pro-oxidative chemo- and radiotherapy synergized with the deactivation of the GAPDH switch, potentially suggesting novel strategies for tumour combination therapy." (PMID 37024754, 2023). "We therefore asked if tumour cells exploit the GAPDH redox switch to survive and grow inside the host environment." (PMID 37024754, 2023). "Together, these observations showed that the GAPDH redox switch allows tumours to counteract oxidative stress that is elevated by either chemo- or radiotherapeutic treatment in vivo." (PMID 37024754, 2023). "PKM, as one of the necessary rate-limiting enzymes for glycolysis, plays an important role in the tumor endocrine and metabolic pathways, while GAPDH, as an important link in the glycolysis pathway, is also important in mitochondrial function." (PMID 37124724, 2023). "ITGB4 expression was examined at the protein level from tumor lysates and normalized to GAPDH levels as detected by WB analyses." (PMID 36932441, 2023). "Inhibiting aerobic glycolysis in the tumor microenvironment by targeting GAPDH, a glycolytic pathway shared by both tumor and immune cells, normalizes trophic competition in TIME and reduces the cytotoxic side effects of immunotherapy." (PMID 36837761, 2023). "GAPDH is a key enzyme in glucose metabolism, and its expression differs between tumor cells and normal cells." (PMID 36837761, 2023). "Quantitative PCR for human GAPDH confirmed that YAP induction dramatically reduced circulating human tumor cells (CTCs)." (PMID 37739954, 2023). "Looking at tumour growth in a mouse xenograft model we found that silencing of the GAPDH redox switch, thus limiting the ability of tumour cells to boost oxPPP flux when needed, substantially limited tumour growth while enhancing endogenous peroxide stress." (PMID 37024754, 2023). "Second, we show that the GAPDH redox switch is functionally relevant in the context of tumour biology, as it supports anchorage-independent growth of single cells and spheroids." (PMID 37024754, 2023).
tumor (continued). "GAPDH, for example, regulates the apoptosis signaling system to increase tumor cell survival by reducing H2O2‐induced programmed cell death and mediated suppression of caspase‐independent cell death." (PMID 35880695, 2023). "Active release of tumor-derived exosomes and glyceraldehyde 3-phosphate dehydrogenase (GAPDH) contributed to generating an immunosuppressive tumor microenvironment through the induction of M2 macrophage polarization." (PMID 37175615, 2023). "Results on the hypoxic regulation of GAPDH are contradictory and seem to be type-specific for various tumor cells." (PMID 36768815, 2023). "Low-dose osimertinib was shown to inhibit GAPDH and tumor endothelial glycolysis and promote vascularization and immune cell infiltration and thus improve the efficacy of anti-PD-1 therapy." (PMID 36768924, 2023). "In a related vein, GAPDH function in tumor cells is controversial; it is important for cancer cell survival, but under oxidative stress, it induces apoptosis." (PMID 37972206, 2023). "It is evident through the heatmap that maximum downregulation was observed with CA7 and minimum downregulation was observed with GAPDH when compared to the TCGA-CRC (tumor and normal) samples." (PMID 37895185, 2023). "The as-prepared FesiRNAPNPs demonstrated specific suppression of GAPDH expression and thus inhibited tumor cell glycolysis, achieving significant synergy with ferroptosis to ablate tumors in vitro and in vivo." (PMID 35473696, 2022). "In the glycolysis event of tumor cells, GAPDH is crucial and overall ATP reduction is largely dependent on GAPDH inhibition." (PMID 36077431, 2022). "While GAPDH-mediated glycolysis and DNA repair promote tumor cell survival, particularly in the presence of damage, GAPDH also has pro-apoptotic functions in response to different stimuli." (PMID 36267982, 2022). "GAPDH overexpression is characteristic of many tumor cells such as breast, lung, pancreatic, kidney, colon, and esophageal tumor for accelerated proliferation." (PMID 36077431, 2022). "The expression of SPI1 was normalized to GAPDH, and results were presented as fold-change in tumor tissues relative to matched adjacent normal tissues." (PMID 35361282, 2022). "GAPDH expression and protein function is altered in many cancer cell types, mainly in response to hypoxic stress in the tumor microenvironment, and is related to tumor progression and invasiveness." (PMID 35893766, 2022). "Numerous reports suggest that gene expression levels of β-actin and GAPDH are affected by many factors under different pathological conditions, such as tumor cells and non-tumor cells, steatosis and alcoholic hepatitis, and Alzheimer’s disease." (PMID 36313673, 2022). "In this context, our finding that GAPDH inhibition leads to tumor regression but accelerated death is particularly striking." (PMID 35205709, 2022). "Tumor cells expressed a meaningful level of associated hypoxic markers depends on their phenotypic changes to normal cells (MCF‐10A), all calibrated by GAPDH (as housekeeping)." (PMID 35079624, 2022). "The de-regulation of GAPDH in tumor tissues or cells demonstrated that the utilization of GAPDH as a reference gene/protein should be chosen very carefully." (PMID 35711943, 2022). "This is the reason why GAPDH inhibitors are effective in the regression of tumor cells, which essentially rely on glycolysis for ATP genesis." (PMID 36077431, 2022). "Taken together, GAPDH was identified as a critical player in the intracellular and extracellular domains for suppressing tumor progression and inflammatory responses." (PMID 35804814, 2022). "Intriguingly, low-dose osimertinib can inhibit GAPDH activity and tumor endothelial glycolysis, thereby promoting adequate vascularization and immune cell infiltration to improve the tumor repression efficacy of PD-1 blockade." (PMID 36200045, 2022).
tumor (continued). "Although GAPDH is often treated as a housekeeping gene, a regulatory analysis revealed its novel anti-tumor, anti-inflammatory action by interacting with L1CAM, an oncogenic transmembrane protein." (PMID 35804814, 2022). "Currently, several GAPDH inhibitors have been known to inhibit GAPDH enzyme activity and proliferation of tumor cells." (PMID 36077431, 2022). "The role of Hsp90ab1 and GAPDH differed in their locations and they acted as the uncommon protectors of the joint tissue from tumor and inflammatory responses." (PMID 35804814, 2022). "The block of glycolytic flux induced by the inhibition of the GAPDH enzyme determines a deep metabolic alteration in the tumour cells." (PMID 35804925, 2022). "High expression of GAPDH, indicating a switch to aerobic glycolysis to meet the metabolic demand for tumor proliferation, has been shown to promote aggressive T cell lymphomas." (PMID 35241665, 2022). "In the obtained FesiRNAPNPs, the GAPDH siRNA silenced the target mRNA to inhibit glycolysis, interfered with tumor energy metabolism, and enhanced Fe2+-induced ferroptosis." (PMID 35473696, 2022). "Although GAPDH is primarily considered an intracellular enzyme for glycolysis, the result herein supported the anti-tumor and anti-inflammatory action of extracellular GAPDH." (PMID 35804814, 2022). "Previous studies showed that GAPDH was involved in apoptosis, the maintenance of DNA integrity, and tumor angiogenesis." (PMID 36467027, 2022). "GAPDH has been attractive as a therapeutic target due to its glycolysis control in the Warburg phenotype of cells such as tumor, activated myeloid and lymphocytic cells." (PMID 36077431, 2022). "A common metabolic change found in tumor cells is elevated levels of glycolysis 58, and glyceraldehyde-3-phosphate dehydrogenase (GAPDH) is a key enzyme involved in glycolysis." (PMID 35280688, 2022). "Our previous results assessing reference genes in Sq-NSCLC showed that GAPDH gene expression was diverse and unstable in tumor and tumor-adjacent normal tissue samples, whereas POLR2A and ACTB expression levels were the most stable among analyzed samples." (PMID 36142417, 2022). "Accordingly, the plck-GAPDH mice showed in their tumor tissues B-cell infiltrates that exclusively demonstrated a GC phenotype (high expression of FAS and GL-7)." (PMID 35625998, 2022). "A growing interest in the study of aerobic glycolysis as a key pathway for cancer-cell energetic metabolism, favouring tumour progression and invasion, has led to consider GAPDH as an effective drug target to specifically hit cancer cells." (PMID 35804925, 2022). "The main enzymes for the preparatory and terminal phases of glycolysis, PFK-1 and glyceraldehyde-3-phosphate dehydrogenase (GAPDH) showed a similar pattern towards increased expression in malignant tumor tissues." (PMID 34073074, 2021). "The anti-tumor effect of MGO is attributed to the inactivation of glyceraldehyde 3-phosphate dehydrogenase (GAPDH), which plays an important role in the high glycolytic capacity of malignant cells." (PMID 34947850, 2021). "GAPDH promotes cancer growth and metastasis through upregulation of SNAIL expression in multiple tumor types and is associated with tumor proliferation, metastasis, and an overall aggressive tumor phenotype." (PMID 33917859, 2021). "It is of importance that the AEAC-mediated release of GAPDH from its complex with Hsp70 and its anti-tumor action depended on GAPDH level." (PMID 33546324, 2021). "Metastatic tumor burden in the lung was quantified by histological analysis of lung nodules and PCR based measurements of human GAPDH expression in the mouse lung." (PMID 34262028, 2021). "This demonstrates that human-specific GAPDH qRT-PCR is more sensitive than histological quantification of lung metastasis in the xenograft tumor model." (PMID 33575432, 2021).
tumor (continued). "Recent evidence suggests that GAPDH plays an important role in tumor cell survival, tumor angiogenesis, gene expression control in tumor cells, and post-transcriptional regulation of mRNA in tumor cells." (PMID 34257558, 2021). "It is based on impairing the energy metabolism of tumor cells by inhibiting enzymes in the glycolysis, HK-II, glyceraldehyde 3-phosphate dehydrogenase, phosphoglycerate kinase, and oxidative phosphorylation, succinate dehydrogenase." (PMID 34899740, 2021). "During cancer therapy, the high energy produced by radiation is aimed to kill tumor cells by turning on their suicide switch, e.g., Glyceraldehyde-3-phosphate dehydrogenase (GAPDH)." (PMID 35008613, 2021). "We therefore used the MDA-MB-436 tumor xenograft model to determine the limits of the human-specific GAPDH-qPCR methods for detecting disseminated cancer cells and if the method would demonstrate that MDA-MB-436 cells are less metastatic than MDA-MB-231 cells." (PMID 33575432, 2021). "In conclusion, the data presented suggest that human-specific GAPDH qRT-PCR provides an efficient, sensitive, and cost-effective method of detecting human tumor-derived mRNA within murine tissues." (PMID 33575432, 2021). "The role of GAPDH in tumor progression has prompted several studies on the effects of GAPDH inhibitor molecules." (PMID 33804240, 2021). "For instance, basis 1 contains classic housekeeping genes, such as GAPDH and ribosomal protein genes (RP-); basis 3 contains well-known tumor-related genes, including EGFR and CDK4." (PMID 34252925, 2021). "Herein, we have described and directly compared the use of human-specific GAPDH qRT-PCR and histological analysis of H&E-stained, fixed thin sections to quantify lung metastasis in murine xenograft tumor models." (PMID 33575432, 2021). "In both in vitro and in vivo models, we showed that increased GAPDH levels reduce the resistance of tumor cells to hypoxia." (PMID 33546324, 2021). "In contrast to healthy cells, where energy is primarily generated by mitochondria, tumor cells primary depend on glycolysis for their energy generation, and GAPDH is a pivotal enzyme in this energy generation." (PMID 35008613, 2021). "Accumulated evidences indicate that GAPDH is deregulated in various cancers under certain conditions and potentially participates in tumorigenesis and tumor progression." (PMID 33630851, 2021). "Previous studies have shown that GAPDH is a regulator of cell death, and GAPDH is involved in tumor progression and has become a new therapeutic target." (PMID 34326892, 2021). "Immunohistochemistry was carried out on Warthin tumor and normal control (parotid gland with striated ducts) tissues, using anti-GAPDH specific antibodies followed by digital image analysis." (PMID 32365590, 2020). "It inhibits the activity of GAPDH, leading to low glycolytic flux and a low cytotoxic response in highly glycolytic tumor cells." (PMID 33256814, 2020). "We used species-specific probes against the human or mouse housekeeping GAPDH RNA to discriminate human tumor cells from normal mouse cells within each tissue section." (PMID 33060293, 2020). "Since the regulation of the senescence mechanisms by GAPDH is strongly dependent on the origin of tumor, this variability should be taken into account when choosing a therapeutic strategy." (PMID 32370188, 2020). "Digital image analysis of anti GAPDH stained Warthin tumor (n = 14) and normal parotid gland (n = 16) tissues was performed to assess the relative level of GAPDH positive Warthin tumor oncocytes in comparison with normal ductal cells." (PMID 32365590, 2020). "GAPDH has been found to play an important role in tumor cell survival, tumor angiogenesis, control of tumor cell gene expression, and post-transcriptional regulation of tumor cell mRNA." (PMID 33221754, 2020). "Tumour and non-tumour tissues in all 20 tissues analysed expressed similar levels ofYBX1,GAPDH,HPRT1,ZFAS1, andAGAP2-AS1 RNAs." (PMID 33447385, 2020).
tumor (continued). "The expression of FADS3 measured against the GAPDH reference gene was higher in the growing tumor area versus the peritumoral area and in the necrotic core versus the peritumoral area, but again the differences were statistically insignificant." (PMID 32392704, 2020). "Previous studies have reported that over-expression of GLUT1, PFKFB3, and GAPDH in endothelial cells is a common feature of tumor-activated endothelial cells, and the inhibition of PFKFB3 leads to vessel normalization and reduces metastasis." (PMID 32244977, 2020). "Hypoxia, which is one of major phenomena accompanying tumor growth, leads to an elevation of GAPDH expression through the activated Hif-1α transcription factor." (PMID 32370188, 2020). "It is likely that the activation of GAPDH synthesis can be considered as a protective mechanism employed by tumor cells in conditions of hypoxia to regulate their metabolism and increase their viability." (PMID 32370188, 2020). "GAPDH staining allowed the identification of tumor boundaries, which was also corroborated by differences in nuclei size, with human cells having larger and rounder nuclei than the surrounding normal mouse tissue." (PMID 33060293, 2020). "As we previously reported in other tumor subtypes, firstly we confirmed the presence of an additional circulating population in patients by means of GAPDH and CD45 expression." (PMID 32423054, 2020). "This means that a high level of GAPDH activity leads to elevated glycolysis intensity, enhancement of tumor growth, and, accordingly, a poor prognosis for patients." (PMID 32370188, 2020). "Another potential anti-tumor drug targeting GAPDH is a natural chemical, koningic acid, which was selected using an advanced approach based on the analysis of the rate-controlling enzymes during the Warburg effect." (PMID 32370188, 2020). "Warthin tumor oncocytes exhibited a markedly spotted GAPDH staining pattern exhibiting cells with cytoplasmic and nuclear, only nuclear or none GAPDH staining." (PMID 32365590, 2020). "This analysis confirmed that Warthin tumor oncocytes exhibit a significantly lower (p < 0.0001) percentage of GAPDH positive cells compared to normal parotid gland ductal cells." (PMID 32365590, 2020). "Inhibiting the GAPDH reaction has the initial effect of reducing the tumor growth rate and flattening the growth curve, compared to the control case." (PMID 31185009, 2019). "On the assumption that a single tumor nucleus contains two copies of GAPDH, 2 × EBV-CN was compared with the number of EBV signals/nucleus." (PMID 30695048, 2019). "Overall, in the case of GAPDH inhibition, tumor volume initially follows the growth curve for the control case, and the effect of inhibiting the GAPDH reaction is only predicted to occur after approximately five days." (PMID 31185009, 2019). "Partial repression of the GAPDH reaction at time zero (Day 0) shows a slightly delayed response in lowering the tumor volume." (PMID 31185009, 2019). "The formation of the complex GAPDH/Akt2 is a mechanism identified in ovarian cancer cells to favor tumor cell survival and to avoid apoptosis." (PMID 31027346, 2019). "We implemented both complete inhibition (at the 0th day of tumor growth) and partial time-based inhibition (0th day, 5th day, 10th day or 20th day) of the three reactions (GAPDH, OXPHOS and ASCT2) independently." (PMID 31185009, 2019). "GAPDH plays an important role in the formation of malignant tumor phenotypes and is considered as a promising target for therapy." (PMID 30967137, 2019). "Complete knockdown of GAPDH has the effect of decreasing fumarate concentration throughout the tumor, with the low level of fumarate (near zero) occurring more rapidly (at the 5th day) and for a longer period of time, compared to the control case." (PMID 31185009, 2019).